KRAS (KRas proto-oncogene, GTPase)
Diseases named in the same sentence as KRAS in open-access papers (continued):
Sharing a sentence is not in itself a finding about the gene and the disease.
tumor (continued). "Preclinical models suggest that combining MEK inhibitors with KRAS G12C inhibitors can reduce the feedback reactivation of the pathway and enhance tumor regression." (PMID 40361439, 2025). "These comparisons enabled us to dissect the distinct contributions of inflammation and KRAS activation to tumor development." (PMID 41285904, 2025). "In patient 3, TCR-T cells generated with TCRs of the top four clonotypes proved to be tumor-specific and three of them recognized a neoepitope derived from oncoprotein KRAS Q61H." (PMID 40165973, 2025). "KRAS mutation status was evaluated alongside PD-L1 expression in tumor cells and HIF-1α expression in both tumor cells and the tumor microenvironment." (PMID 39996842, 2025). "Immunoblotting of the tumor protein extracts showed that in the USP25-depleted tumors KRAS protein levels as well as the phosphorylation levels of MEK and ERK were all downregulated." (PMID 40473213, 2025). "Tumor vascularization is further supported by KRAS-mediated induction of hypoxic HIF signaling, which increases the expression of VEGF (vascular endothelial growth factor)." (PMID 39858030, 2025). "We observed similar results with a second tumor cell line, A549, which is an HLA-A2+ KRAS-mutant NSCLC cell line." (PMID 40459946, 2025). "We report that KRAS wild-type (WT)–amplified tumor models are sensitive to treatment with the small-molecule KRAS inhibitors BI-2493 and BI-2865." (PMID 39711431, 2025). "Although high tumor mutational burden (TMB) in PDAC has been reported to be associated with favorable ICI efficacy and low KRAS mutation rates, the link was indirect." (PMID 40611261, 2025). "In vivo studies have demonstrated that LY3537982 monotherapy led to tumor growth inhibition and induced tumor regression when used in combination with other KRAS G12C-targeting drugs." (PMID 40597785, 2025). "DHX15 bound to FN1859 on the surface of Fusobacterium nucleatum, mediating the tumor‐promoting role of Fusobacterium nucleatum in KRAS G12D mutant tumors." (PMID 40485603, 2025). "IL-8 is a direct transcriptional target of KRAS signaling and promotes angiogenesis, inflammation, and tumor progression." (PMID 40524071, 2025). "The nomograms incorporate clinicopathological and laboratory data, including tumour size, multifocality, tumour burden score, KRAS status, vascular invasion, nodal involvement, presence of cirrhosis, and preoperative serum tumour marker levels." (PMID 39867595, 2025). "This prospective study demonstrated that the early clearance of KRAS G12C–mutant ctDNA predicted increased tumor response as well as longer survival in patients with advanced NSCLC who received sotorasib treatment in a real‐world setting." (PMID 40445863, 2025). "It is widely known that expression of oncogenic KRAS activates cellular growth arrest through downstream signaling of tumor-suppressor pathways." (PMID 39412982, 2025). "The resistance is accompanied by increased NOS2 and •NO production, which promote tumour growth and reduce the effect of anti-KRAS drugs." (PMID 40567499, 2025). "Complementary strategies, including SOS1 inhibitors and pan-KRAS inhibitors, are actively being developed to enhance efficacy and overcome tumour resistance." (PMID 41303058, 2025).
tumor (continued). "Clinically, molecular biomarkers—including KRAS/NRAS/BRAF mutations, HER2 amplification, PIK3CA mutations, MSI/MMR status, and the tumor microenvironment—play an important role in therapeutic decision-making." (PMID 40805234, 2025). "Following RNA isolation, using stem-loop quantitative reverse transcription PCR (RT-qPCR) to detect individual guide strands, we confirmed that the GE11-mediated delivery platform delivered MYC and KRAS siRNAs to the tumor." (PMID 40762837, 2025). "The results highlight our method’s capacity to directly select tumor-specific TCRs for therapy and suggest the mutant KRAS-specific TCRs as candidates for an off-the-shelf TCR-T therapy in HLA-A*01:01-positive patients with RAS Q61H-positive tumors." (PMID 40165973, 2025). "Cell death in both settings depended on p38, which is also required for tumor progression driven by KRAS or PI3K." (PMID 39805854, 2025). "KRAS mutations activate the MAPK-NRF2 axis, leading to the elevated expression of FSP1 and conferring resistance to ferroptosis in tumor cells." (PMID 40862825, 2025). "Given the crucial role of mutant KRAS in tumour initiation and progression, the development of therapeutics specifically targeting KRAS mutants hold great potential for tumour suppression." (PMID 39820726, 2025). "Of importance, this synergistic approach not only disrupts KRAS-driven oncogenesis but also amplifies immunostimulatory signaling, culminating in enhanced tumor suppression even in poorly immunogenic tumor models." (PMID 40585984, 2025). "Progression-free survival on alectinib was 11.5 months until KRAS amplification emerged on serial circulating tumor DNA analysis, leading to rapid systemic relapse." (PMID 41246301, 2025). "Our study successfully engineered MEG-01 cells to produce PLPs carrying oncogenic KRAS, demonstrating the efficient transfer of this oncogene to tumor cells and its significant impact on enhanced proliferation and drug resistance." (PMID 40244100, 2025). "We also used Sanger sequencing to detect six genes—KRAS, NRAS, HRAS, TERT, RET, and BRAF—in the tumor tissue and identified a C228T mutation in the TERT promoter region." (PMID 41488090, 2025). "After the tumor volume reached around 80~100 mm3, 100 μg HLA-A2/KRAS G12V-CD3 BiTE was given intravenously every 2 days, 1×107 T cells and 200 μg DSPE-PEG-iRGD every 4 days." (PMID 41472736, 2025). "In preclinical models, KRAS G12C inhibitors have shown significant synergistic anti-tumor effects when combined with anti-PD-1 therapy." (PMID 40303413, 2025). "On the other hand, it also displayed alterations in the expression of key genes, including SOX9, E2F family, KRAS, BCL2L1, and MYC, indicative of a predisposition for BC tumor initiation, stemness, and progression." (PMID 40801146, 2025). "KRAS allelic imbalances are frequently observed (55%) in mutant KRAS–driven cancer across many different tumor types." (PMID 39412982, 2025). "KRAS mutations activate downstream signaling cascades, including the MAPK (RAS-RAF-MEK-ERK) and PI3K-AKT-mTOR pathways, which drive tumor growth and survival." (PMID 40361439, 2025).
tumor (continued). "Approximately 50% of CRC-harboring mutations in the KRAS gene exhibit hyper activation of the MAPK signaling pathway, potentially accelerating tumor progression." (PMID 41515982, 2025). "The combination of these antibodies with KRAS inhibitors has shown improved control of tumor compared to monotherapy, and is one of the most promising areas of exploration at this stage, with multiple clinical trials currently underway." (PMID 40485603, 2025). "In the total tumour mass, direct effects of KRAS expression inhibition on mRNA and protein levels, as well as indirect effects of tumour growth inhibition and tumour cell death induction, were found." (PMID 39434498, 2025). "We next used the GEPIA database to determine which proteins have an expressional correlation with PRMT5 and KRAS in CRC patient tumor samples." (PMID 40864819, 2025). "Overall, treatment with Divarasib resulted in durable clinical responses across KRAS G12C-positive tumour with mostly low-grade adverse events." (PMID 39820726, 2025). "Less well understood is the extrinsic effect of modulating oncogenic KRAS on the tumor microenvironment." (PMID 39782689, 2025). "These include the emergence of bypass signaling or alternative oncogenic drivers, such as KRAS mutations or activation of the PI3K pathway, as well as changes within the tumor microenvironment." (PMID 40688855, 2025). "KRAS is among the most commonly mutated genes in NSCLC, especially in adenocarcinomas, and contributes to tumor progression and metabolism." (PMID 40558308, 2025). "One mechanism is by inducing IL-6 trans-signalling by shedding sIL-6R, a process particularly important in KRas-mutant cancers, where it promotes tumour growth and progression, contributing to resistance against EGFR-targeted therapies." (PMID 40427200, 2025). "Emerging evidence links KRAS mutations to ICI efficacy, potentially due to their impact on tumor immunogenicity and the microenvironment." (PMID 40558308, 2025). "Comparison to additional metrics revealed that tumors with putative mutant KRAS-specific clones present had increased TCRβ tumor repertoire richness, diversity and tumor-distinct clones." (PMID 39789181, 2025). "In contrast, tumor mutational status, particularly mutations in driver genes such as EGFR, KRAS, and STK11, has recently emerged as a more stable predictor of immunotherapy response." (PMID 40777022, 2025). "Molecular studies have also revealed common colon and pancreatic genetic alterations that sustain tumor progression, such as Kirsten rat sarcoma viral oncogene homolog (KRAS) aberrations." (PMID 40013338, 2025). "Our analysis suggested LURAP1L-AS1 to act as a molecular sponge for miR-7a-5p, miR-101-3p, miR-181a-5p, and miR-27a-3p, resulting in the upregulation of EZH2, MCL1, and KRAS, among other tumor promoting." (PMID 39995981, 2025). "Administration of PD901 in the KRAS-driven iCCA mouse model resulted in a marked increase in apoptosis within tumor tissues." (PMID 40723336, 2025). "BN1 effectively inhibited KRAS transcription and translation in tumor cells, resulting in the downregulation of phosphorylated MEK and ERK, as well as the induction of cell apoptosis and cell cycle arrest." (PMID 40885393, 2025). "Among the findings, the dataset highlighted significant associations between imaging features such as tumor size, texture, and [18F]FDG-PET uptake, with key oncogenic mutations (e.g., EGFR, KRAS, ALK) and survival outcomes." (PMID 40192792, 2025). "The KMPAG signature, in particular, highlights genes that potentially modulate both macrophage polarization and tumor cell behavior, suggesting that complex crosstalk between KRAS-activated cells and infiltrating macrophages fuels disease progression." (PMID 40607411, 2025).
tumor (continued). "Incorporating the pharmacological agent significantly modified the conformation of KRAS proteins, which in turn influenced the status of tumor cells." (PMID 40390765, 2025). "Further Cox analysis to include KRAS subtype status and tumor grade was performed on the TCGA cohort after the exclusion of low-occurring KRAS subtypes (G12A, G12C, Q61R)." (PMID 40243415, 2025). "Quantitative analysis of tumor-specific mutations in ctDNA, such as single nucleotide variants in KRAS, NRAS, PIK3CA, BRAF, and EGFR, demonstrated over 80 % concordance with tumor tissue in patients with colorectal, lung, and breast cancers." (PMID 40144458, 2025). "Association of the expressions of SRC, JUNB, FOSB and PD-L1 as well as clinicopathological characteristics in tumor samples of KRAS-mutant NSCLC patients." (PMID 40599804, 2025). "Apart from driving tumourigenesis, mutant KRAS can also affect the tumour microenvironment (TME) by regulating cytokine release, recruitment of immune cells to the tumour sites for enhanced inflammatory responses as well as facilitating immune escape." (PMID 39820726, 2025). "In multiple KRAS‐mutant tumor cell lines, COA4 is consistently upregulated, and its knockdown partially reverses KRAS‐induced invasion and migration, establishing COA4 as a critical downstream effector of KRAS in promoting tumor metastasis." (PMID 40936169, 2025). "addressed the heterogeneity of the mutations predicting the resistance to anti‐EGFR treatment (KRAS, NRAS, BRAF and/or PIK3CA) in the primary CRC tumours in the context of the proportion of neoplastic cells." (PMID 40302146, 2025). "In a xenograft tumor model harboring the KRAS‐G12V mutation, the TCR engager displays substantial tumor suppression efficacy." (PMID 40470869, 2025). "Prior studies have shown that oncogenic KRAS signaling enhances tumor cell fitness by promoting stress granule biogenesis." (PMID 41190067, 2025). "MRTX1133 is a selective non-covalent inhibitor that binds the inactive GDP-bound form of KRAS G12D and has demonstrated potent tumor regression in PDAC mouse xenograft models, including near-complete responses in some cases." (PMID 40806185, 2025). "Regarding the cell migration point, both the KRAS and PIK3CA mutations promote cell migration, leading to aggressive tumor growth and metastasis." (PMID 40806644, 2025). "LY3537982, another KRAS G12C inhibitor with a lower IC50 compared to both AMG510 and MRTX849, demonstrates potent anti-tumour efficacy, including complete regression in KRAS G12C tumours." (PMID 39820726, 2025). "Molecular analysis identified a KRAS/NRAS wild-type tumor, which allowed the use of panitumumab as a targeted therapy." (PMID 40863225, 2025). "Here, we show for the first time the anticancer effects of the pan-KRAS inhibitors BI-2865 and BI-2493 in preclinical models of KRAS WT–amplified cancers of different tumor origin." (PMID 39711431, 2025). "Deleting YAP stops tumor progression while sparing normal tissue, highlighting its specific role in KRAS‐driven cancers." (PMID 40895190, 2025). "Macrophages are well-studied subjects in innate tumor immunity and play a cancer-promoting role in the microenvironment of KRAS mutant tumors." (PMID 40611261, 2025). "Next generation sequencing of the tumor at baseline showed microsatellite instability high (loss of MLH1 and PMS2 and TMB 15, ARID1A G801FS*32, KRAS Q6H, PIK3CA N1044K, PTEN R130G, SMARCA4 P109FS*194 and SMARCA4 P316FS*10 mutations)." (PMID 40382524, 2025).
tumor (continued). "They orchestrate LD formation within tumor tissues via intricate pathways linked to inflammation, hypoxia, and acidosis, intersecting with key oncogenic pathways like PTEN, KRAS, and FOXO3/Sirtuin6." (PMID 41041279, 2025). "Here, we analyze the emerging topic of KRAS allelic imbalances and how it arises during tumor evolution, as it is often detected in advanced and metastatic PDAC." (PMID 40227826, 2025). "KRAS mutant tumours deviate from their baseline copy number state significantly less than KRAS wild-type tumours (FDR = 0.0014)." (PMID 41509216, 2025). "Similar to shared neoantigens such as mutant KRAS, personalized neoantigens are selectively expressed on tumor cells and have strong affinity for MHC, thus evading central tolerance and mitigating the toxicity caused by the lack of specificity of TAAs." (PMID 40227779, 2025). "In cases where KRAS hyper-exchange mutations disrupt the regulatory function of GTPase-activating proteins (GAPs), KRAS remains in a continuously active state, fueling uncontrolled tumor growth and promoting resistance." (PMID 39852181, 2025). "Strong specific inhibition of KRAS G12C was demonstrated in both a cellular model and a nude mouse xenograft tumor model." (PMID 40303413, 2025). "Tipifarnib (R115777; Zarnestra), the first non-peptidomimetic FTI tested in clinical trials, demonstrated significant tumor inhibition, although it was only partially effective against KRAS-mutant cells (NCT00006199)." (PMID 40597785, 2025). "Nevertheless, few KRAS G4 ligands have been discovered to date, let alone their potentials and mechanisms on tumor therapy." (PMID 40885393, 2025). "Preclinical models demonstrate 60–80% tumor growth inhibition in KRAS-mutated NSCLC with minimal systemic toxicity, underscoring the therapeutic window created by tumor-selective copper accumulation." (PMID 41291133, 2025). "We previously published that κB-Ras deficiency interfered with acinar regeneration and promoted mutant KRas-induced cancer development in vivo, suggesting a tumor-suppressive role of the κB-Ras:RalGAP complexes." (PMID 40490362, 2025). "Subsequent research found that analysing a single tumour block resulted in inaccurate KRAS and BRAF status in 10%–30% of cases, requiring multi‐region analysis." (PMID 40302146, 2025). "The significant contribution that KRAS, BRAF, and NRAS mutations predominate in serous borderline precursors suggests a stepwise model for tumor development and reinforces the importance of MAPK signaling in the biology of disease." (PMID 41376748, 2025). "This study aimed to illuminate the association between physical activity and the risk of CRC by tumor molecular subtypes (microsatellite instability, CpG island methylator phenotype, BRAF, and KRAS mutation status)." (PMID 41031512, 2025). "Recently, MRTX1133, a noncovalent, selective inhibitor of KRAS G12D, was discovered and proven to be effective in a KRAS G12D mutant xenograft mouse tumor model." (PMID 39972450, 2025). "KRAS mutations are associated with a more aggressive tumor phenotype and reduced survival rates in CCA, highlighting the potential of mutant KRAS as a therapeutic target." (PMID 41226789, 2025). "Other studies, in turn, indicate a predictive effect of KRAS on LC compared to wild-type KRAS tumours." (PMID 41228322, 2025). "We also focus on the main driver oncogene, KRAS, and discuss how different allelic frequencies arise during tumor progression and how they affect tumor biology." (PMID 40227826, 2025).